BRCA2 (BRCA2 DNA repair associated)
Diseases named in the same sentence as BRCA2 in open-access papers (continued):
Sharing a sentence is not in itself a finding about the gene and the disease.
cancer (continued). "The overall annual incidence rates irrespective of age in those who had no prior or prevalent cancer, were 2.7% for BRCA1 founder mutations, 3.6% for less frequent BRCA1 mutations, and 2.5% for BRCA2 mutations." (PMID 20180971, 2010). "We also estimated the overall mortality in the absence of any cancer for BRCA1 and BRCA2 mutation carriers separately." (PMID 19277124, 2009). "This implies that the risk of cancer is most likely higher than those with a ‘true negative’ (i.e., those with a negative genetic test result in a family with a known BRCA1 or BRCA2 mutation) genetic test result." (PMID 19088722, 2009). "In contrast, studies have also shown that SNP309 G/G alone does not have an effect on the risk or the onset of various cancers, including familial breast cancer in which mutations for BRCA1 or BRCA2 have not been detected." (PMID 19226467, 2009). "On the other hand, BRCA2, but not the BRCA1 gene, was significantly linked to the development of cancer outside the breast–ovarian axis." (PMID 19329713, 2009). "There is no reason to believe that carriers of BRCA2 mutations should have greater mortality than men with BRCA1 mutations from non-cancer causes, and men with other forms of cancer were excluded." (PMID 18577985, 2008). "Incorporation of these additional cancer phenotypes into the model should provide greater discrimination between BRCA1 and BRCA2 mutation carriers and noncarriers." (PMID 18349832, 2008). "In particular, we wished to assess the occurrence of specific cancer subtypes in first, second and third degree relatives of MBC probands in families with and without BRCA2 predisposing mutations." (PMID 16764716, 2006). "In particular, we wished to assess the occurrence of specific cancer types in relatives of MBC probands in families with and without BRCA2 predisposing mutations." (PMID 16764716, 2006). "The results presented here support these findings, since we detected BRCA2 changes almost twice as frequently in patients without cancers among first degree relatives compared to patients with cancers diagnosed in parents or siblings." (PMID 12373604, 2002). "While some genes, such as BRCA1 and BRCA2, have long been known to make a significant contribution to the familial aggregation of certain cancers, the more general question has not been definitively answered since most genes have not been extensively evaluated in association studies." (PMID 40073867, 2025). "Additionally, we did not have the primary tumor of one of the patients with BRCA2 methylation for comparison, so we are unable to say if this methylation is something that occurred during the metastatic progression of the cancer." (PMID 39392573, 2025). "There were no other cancer-related germline mutations, including BAP1, BRCA1, or BRCA2." (PMID 40283643, 2025). "Indeed, such cancers are over-represented among BRCA1 and BRCA2 carriers." (PMID 40338860, 2025). "For BRCA2‐associated cancers where validated cancer‐specific PGS are available (breast, prostate, pancreas, ovary, larynx, lung, and oral), each PGS was associated with the respective cancer risk, independent of BRCA2 PV carrier status, p < 0.001." (PMID 40462315, 2025). "Other cancer germline mutations, such as BAP1, BRCA1, or BRCA2, were negative." (PMID 40283643, 2025).
cancer (continued). "When the clinical characteristics of the study groups were compared, stratified by BRCA2-positive and BRCA2-negative status for each cancer type, the cohort included 102 BRCA2-negative and 14 BRCA2-positive BC cases, as well as 15 BRCA2-negative and 4 BRCA2-positive OC cases." (PMID 41283249, 2025). "Second, the TCR database does not include personal-level data of patients with cancer, so we lacked some information including family history, social history, BRCA1/BRCA2 mutations, comorbidities, and personal history of cancer, which are factors known to affect MBC incidence." (PMID 38275884, 2024). "‘Metabolic bypass’ of Knudson's paradigm in this way might represent a widespread mechanism used by cancer cells to overcome intrinsic tumour suppressor mechanisms – and possibly, not just those executed by BRCA2." (PMID 39711301, 2024). "The uptake rates of surgical prevention could be lower in carriers of BRCA1/BRCA2 PVs identified from population-based testing, particularly in the absence of cancer within the family." (PMID 39264630, 2024). "Thus, there are indications that BRCA2 carriers with ER+ cancer would benefit more from chemotherapy than non-carriers with ER+ cancer." (PMID 38036573, 2023). "Although we did not compare the findings of mammography between BRCA1 and BRCA2 patients, the higher rate of echogenic foci in BRCA2 cancers might suggest the importance of mammography in BRCA2 patients." (PMID 36905492, 2023). "Experimental evidence suggests exogenous aldehyde reduces levels of BRCA2, not BRCA1, and the low levels of BRCA2 could induce genome instability and cancer." (PMID 36345163, 2023). "In our study, the expressions of BRCA2 and XPD are probably elevated in tumour tissue and blood of patients in the early stages of cancer in an effort to increase the DNA repair capacity, which is essential for promoting tumour growth, and the cancer phenotype." (PMID 37113717, 2023). "Furthermore, treatment with the PARP inhibitor olaparib upregulates PD-L1 expression through the formation of cytotoxic DSBs and activation of ATM/ATR/Chk1 kinases in BRCA2-depleted cancer cells independent of the IFN pathway." (PMID 37174127, 2023). "The National Comprehensive Cancer Network (NCCN) recommends a BRCA2 genetic test starting at age 40 years in cases of a personal history of metastatic, node-positive, biochemically recurrent, Gleason ≥8, or Gleason 7 disease with a strong family history of BRCA-related cancers." (PMID 36612302, 2023). "Numerous studies have shown that HDACi treatment across various cancer cell lines also results in the transcriptional downregulation of genes involved in homologous recombination and nonhomologous end-joining (Ku70, Ku86, DNA-PKcs, RAD51, BRCA1, and BRCA2), which are critical for DSB repair." (PMID 37991020, 2023). "However, the involvement of BRCA2 should not be expected since BRCA2-mutant cancers do not show typical ~10-kb MH-mediated TDs4,6." (PMID 35879372, 2022). "Interestingly, certain types of cancer, such as Ewing’s sarcoma, do not harbor mutations in BRCA1 or BRCA2, but they still are sensitive to PARP inhibitors." (PMID 36613695, 2022). "While prevalences for ATM, BRCA1, BRCA2, and PALB2 in this study are consistent with prevalences observed in the literature, we calculated that as many as 1.22% of individuals in both cohorts unselected for personal or family history of cancer harbored GPV in CHEK2." (PMID 35805029, 2022).
cancer (continued). "However, HR-deficient cells lacking BRCA1 or BRCA2 show specific susceptibility to PARP1 inhibition, whereby accumulation of genetic lesions and ensuing chromosome instability in fast-dividing cancer cells results in their death." (PMID 35018214, 2022). "The most frequently amplified genes across the pan-cancer atlas were BRIP1 (HDR, 8.04%), POLB (BER, 6.54%), MUS81 (HDR, 6.42%), NBN (HDR, 6.31%), and EXO1 (MMR, 6.26%), while the most frequently deleted genes were BRCA2 (HDR, 6.44%), XRCC2 (HDR, 6.38%), and CUL5 (NER, 6,28%)." (PMID 36081518, 2022). "Such agents are also of specific interest in cancers that harbor defects in DDR pathway components, where they may create a synthetic lethal-like interaction, as in the case of poly (ADP-ribose) polymerase (PARP) inhibitors in BRCA1 or BRCA2 mutant cancers." (PMID 36309653, 2022). "Importantly, cancer risks differ between BRCA1 and BRCA2 PVs as well as by sex." (PMID 36497436, 2022). "Therefore, we tested the effects of WRN helicase inhibition on the survival of cancer cells lacking functional BRCA2." (PMID 34772932, 2021). "However, comparison with population controls detected an increased occurrence in childhood cancers in families with a BRCA2 PGV, but not BRCA1." (PMID 34680915, 2021). "The results of differential gene expression analysis show that in BC and OV cancers, there is a variation of gene expression profiles in patients with somatic or germline BRCA1/BRCA2 mutations, compared to patients without mutations, as well as between mutation types for the same gene." (PMID 33525353, 2021). "This statement may not be applicable to BRCA2, as the latter gene is not essential for taxane-driven killing of cancer cells." (PMID 34454564, 2021). "BRCA1 or BRCA2 negative cancers cannot use the HR pathway to repair DNA DSBs." (PMID 33926008, 2021). "As regards the association with overall cancer risk, the OR of LOF variant carriers versus nonsynonymous variant carriers was 1.53 (95% CI: 0.80–2.92) and 1.14 (95% CI: 0.40–3.22) for BRCA1 and BRCA2, respectively." (PMID 33266155, 2020). "The presence of BRCA1 germline alteration is more closely involved in HRD than that of BRCA2, and it is anticipated that BRCA-associated cancer may be differentiated even in the absence of BRCA1 germline mutation if a similar expression profile is exhibited." (PMID 32719318, 2020). "Furthermore, the BRCA2 c.7008_2A>T (IVS13-2A>T) mutation, is unlikely to contribute to cancer risk in the context of the allele described here, since it lies downstream of another mutation that completely abolishes the synthesis of a functional gene product." (PMID 33287145, 2020). "We speculate that this deletion of BRCA2 was de novo, as this SA Indian BC patient did not report a family history of cancer." (PMID 32375709, 2020). "Heterozygous mutations of BRCA2, BRIP1 (FANCJ) and PALB2 (FANCN) are not sufficient to develop FA phenotypes, but they are associated with a dramatic increased risk for breast, ovarian and other cancers." (PMID 31535215, 2019). "PTEN, BRCA1, and BRCA2 proteins play an important role in resisting the growth of BREAST cancer, while PI3K and CCND1 proteins could improve the growth of BREAST cancer." (PMID 30792708, 2019). "It is well accepted that downregulation of BRCA1 and BRCA2 leads to PARP inhibitor sensitivity, and our data suggest that TIGAR KD induces “BRCAness” by phenocopying the gene expression pattern produced by BRCA1/2 downregulation and thereby sensitizes cancer cells to olaparib." (PMID 31508509, 2019).
cancer (continued). "Importantly, SOX17 transcriptionally down-regulated DNA repair and damage response-related genes including BRCA1, BRCA2, RAD51, KU80 DNAPK, p21, SIRT1, NFAT5 and REV3L in KYSE510 radio-resistant cells to achieve the sensitization effect to anti-cancer treatment." (PMID 30777052, 2019). "Cancer incidence rate per 1,000 person years was higher in BRCA2 carriers than non-carriers (19.4 vs 12.0;p=0.03); BRCA2 carriers were diagnosed younger (61 vs 64years;p=0.04) and were more likely to have clinically-significant disease than BRCA2 non-carriers (73% vs 40%;p=0.03)." (PMID 31591445, 2019). "We focused on the cancer’s earliest age of onset in the subject with double heterozygosity and a careful examination of literature revealed that this is in agreement with previous findings and was not unexpected in patients carrying double heterozygosity for BRCA1 and BRCA2 genes." (PMID 29346284, 2018). "Paradoxically, loss of BRCA2 in normal cells leads to cell cycle arrest and apoptosis due to the activation of the DNA damage response (DDR) rather than unrestrained proliferation, characteristic of cancer cells." (PMID 29416040, 2018). "For example, the identification of synthetic lethal interactions between BRCA1 or BRCA2 tumour suppressor genes and inhibition of the PARP1 DNA repair protein has driven the clinical development and approval for use of PARP inhibitors for the treatment of cancer." (PMID 29915391, 2018). "The reason of the“compensatory” upregulation of BRCA2-mRNA in lowBRCA1-expressing cancers remains speculativebecause there is no exact knowledge on how the BRCA protein expression is regulatedeither in normal or in malignant tissues." (PMID 30111871, 2018). "For example, TBPT significantly suppressed a series of genes involved in DNA double-strand break repair, including LIG4, CENPF, DNAJC2, RECQL, SMC6 and BRCA2 (≥ 2-fold), which are also considered vital targets for treating cancer cells without affecting normal cells." (PMID 26986511, 2016). "However, unlike cancer, the function of proteins involved in DNA damage response, such as BRCA2 and TOP2A, does not show uncoordinated functions." (PMID 26975659, 2016). "The use of PARP enzyme inhibitors in cancer cells which are defective for BRCA1 and BRCA2, two proteins that localize the RAD51 recombinase to the sites of damaged DNA and promote HR repair, represent the best and most successful synthetic lethal approach in cancer therapy." (PMID 27884198, 2016). "Combining IDO and BRCA2 downregulation did not sensitize cancer cells to 5FUdR." (PMID 26579709, 2015). "However, due to the small number of mutation carriers in the SEARCH dataset, it was not possible to estimate reliably the cancer risks for BRCA1 and BRCA2 mutation carriers." (PMID 26025000, 2015). "Notably, concurrent downregulation of IDO and BRCA2 did not sensitize cancer cells to 5FUdR to any greater degree than knockdown of BRCA2 alone (lane 5 vs. lane 6)." (PMID 26579709, 2015). "Adjuvant tamoxifen treatment may be another option to decrease the risk of cancer occurrence for individuals with BRCA1 and BRCA2 mutations who decide not to undergo preventative surgery." (PMID 24830819, 2014). "Among the ten genes, five of the TSGs (ATM, APC, BRCA2, NF1, and PTEN) were annotated with positive effects on apoptosis; the other three TSGs (PEG3, SPARC, and RPS6KA2) were also reported to increase apoptosis in sporadic epithelial OVC or other types of cancer." (PMID 22952919, 2012). "Furthermore, the results of the functional assays are difficult to quantify and do not necessary reflect the influence on cancer risk, since BRCA1 and BRCA2 are multifunctional." (PMID 19563646, 2009).
cancer (continued). "However, no such influence is seen for BRCA1 or BRCA2 cases, which often have a much stronger family background of cancer." (PMID 15642173, 2005). "Patients were categorised based on germline classification as BRCA1 positive (N = 27), BRCA2 positive (N = 21), and BRCA1/2 negative (N = 232), excluding those with BRCA1/2 variants of uncertain significance (N = 8) and pathogenic or only uncertain variants in other cancer genes (N = 62)." (PMID 41797047, 2026). "Moreover, the survival of BRCA1- or ATM-deficient cancer patients could be triaged by SETD1A expression, which was not the case for those with deficiencies in BRCA2, nor those with functional copies/levels of these genes." (PMID 39994444, 2025). "We find that loss of CSB and BRCA2 is a toxic combination to genomic stability and cell survival at a high concentration of CPT, which is likely due to accumulation of ssDNA gaps, underscoring an important role of CSB in regulating the therapy response in cancers lacking functional BRCA2." (PMID 37569794, 2023). "Currently, there are no effective cancer screening methods for OC or prevention strategies to reduce OC risk in the general population, although prophylactic salpingo-oophorectomy has been proven to reduce risk in carriers of pathogenic BRCA1 or BRCA2 variants." (PMID 36833203, 2023). "Further investigation of the revealed founder variants in other cancers in Kazakhs could lead to overlapping results, as these PVs cause truncated or absent BRCA1 and BRCA2 proteins and have already been found in other malignancies where loss of function is a known disease mechanism." (PMID 37791908, 2023). "Indeed, there are many papers that describe the detection of positive selection signals in BRCA1 and BRCA2 despite the fact that selective pressures on human cancer genes throughout mammalian evolution might not be directly associated with cancer." (PMID 38275383, 2023). "For example, cells with mutations in BRCA1 or BRCA2 cannot perform DNA double-strand break (DSB) repair by homologous recombination (HR), and accumulate genetic lesions through alternate use of nonhomologous end joining (NHEJ) that directly leads to cancer development." (PMID 35018214, 2022). "In the case of tumor cells with deficiency in BRCA1 or BRCA2, loss of CSB expression would also predict that these cancer cells would not be able to depend upon BIR for survival and might turn to different salvage repair pathways such as alternative end joining, which in turn could be targeted." (PMID 36142121, 2022). "Since MC180295 could suppress the expression of BRCA1 and BRCA2, DNA damage response for double-stranded DNA breaks was disrupted in the MC180295-treated EBVaGC cells, indicating that the combination of MC190285 and a PARP inhibitor might lead to cancer-cell-specific death." (PMID 36142506, 2022). "Not only does the patient now know their BRCA2 gene is not normal (deviates from the wild-type sequence), the clinical significance of the VUS findings are rarely known, leaving the patient with unknown future cancer risk." (PMID 34065235, 2021). "Although BRCA1 and BRCA2 as double-stranded DNA repair genes preferentially promote tumorigenesis of breast and ovarian epithelial cells, supportive evidence still exists that shows that BRCA1/2 might play a role in the progression or prognosis of other cancer types." (PMID 32879886, 2020). "Thus, firstly, we identified all rare variants both exome-wide and cancer-associated gene panel-wide (492 genes) in 54 BC patients from BRCA1 and BRCA2-negative families with elevated BC risk and compared their relative incidence in 120 geographically matched controls." (PMID 30947698, 2019). "Notably, when STRING network analysis was used to investigate functional interactions, this revealed a DDR cluster that included BRCA1 and BRCA2, as well as their interacting tumour suppressor partners PALB2 and BAP1, two cancer-associated DDR genes not previously indicated as G4 ligand sensitisers." (PMID 31287417, 2019).